IL1B (interleukin 1 beta)
Diseases named in the same sentence as IL1B in open-access papers (continued):
Sharing a sentence is not in itself a finding about the gene and the disease.
gout (continued). "Collectively, our results indicate that SHA has inhibitory effects on inflammation and gouty arthritis primarily by intervening in the formation of inflammasomes and lessening the proinflammatory cytokines of TNF-α and IL-1β." (PMID 34284768, 2021). "Polarization into the M1 phenotype promotes the production of proinflammatory cytokines IL-1β and TNF-α that further aggravate gout." (PMID 33505510, 2021). "The expression of IL-1β and TNF-α in the joint synovial fluid of MSU-induced GA rats in the model group was significantly increased, suggesting that inflammatory factors such as IL-1β and TNF-α play an important role in acute episodes of gout." (PMID 34721647, 2021). "While the activation of IL-1β and the role of NLRP3 in gout have been relatively well-established, the upstream pathways involved in MSU-triggered NLRP3 activation are not yet fully understood." (PMID 33926105, 2021). "For patients with gout refractory to NSAIDs and colchicine, the FDA has approved the use of an anti-IL-1b antibody, canakinumab, for gout inflammation." (PMID 34104597, 2021). "In gout and acute CPP crystal arthritis, the crystals taken up by macrophages first enhance pro-IL-1β expression during the priming phase and then promote the assembly and activation of the NLRP3 inflammasome." (PMID 33926523, 2021). "In a mouse gouty arthritis model, oral administration of CAPE inhibited MSU crystal-induced caspase-1 activation and IL-1β production in air pouch exudate and foot tissue thus attenuating inflammatory symptoms." (PMID 33534121, 2021). "The CPT1A hypomethylation observed here therefore likely promotes gout by increasing CPT1A expression and IL-1β production in macrophages." (PMID 33493135, 2021). "In gout, monosodium urate (MSU) crystals activate the NLRP3 inflammasome, induce the release of IL-1β and promote the development of arthritis." (PMID 34830282, 2021). "PBMCs isolated from gout patients carrying this SNP expressed higher level of NLRP3, and the plasma level showed significantly increased IL-1β cytokine level." (PMID 33717162, 2021). "To understand the immunomodulatory effects of DcR3 on gout, we compared the effects of DcR3.Fc and HBD.Fc on MSU-induced IL-1β secretion in LPS-primed M-Mφ and GM-Mφ." (PMID 33746978, 2021). "In this investigation, we aimed to quantify the pro-inflammatory response of normal and gout PBMCs towards combined TLR2 ligand and urate crystal stimulation with a particular focus on monocytes’ phagocytic activation and downstream IL-1β secretion." (PMID 34992596, 2021). "These inflammatory cytokines (IL-6, IL-8, IL-1β, and TNF-α) exert differential effects on vascular inflammation and dysfunction in patients with gout, a condition characterized by hyperuricemia." (PMID 33330657, 2020). "Two following works established the importance of IL-1β in CIA and laid the foundation for the definition of gout as autoinflammatory disease." (PMID 32426360, 2020). "Procyanidins attenuated gout pain and suppressed ankle swelling and inhibited MSU-induced activation of the NLRP3 inflammasome and increase of IL-1β." (PMID 32973552, 2020). "A Monosodium urate (MSU) and CPPD crystal activate the production of IL‐1β in the nod‐like receptor protein‐3 (NLRP3) inflammasome, resulting in gout and pseudo‐gout attacks." (PMID 32608157, 2020). "Neutrophilic infiltration and subsequent NETosis, a feature of inflamed joint in gout patients 28, exposes self-DNA, which is suspected - once phagocytozed - to induce AIM2-dependent IL-1β secretion (reviewed in 29)." (PMID 32104502, 2020). "In this study, we found that IL-1β, TNF-α, and IL-6 were significantly increased in synovial tissues and serum of MSU-induced rat gout models, which is consistent with the characteristics of the GA inflammatory reaction." (PMID 32774151, 2020).
gout (continued). "In a murine gouty arthritis model, the oral administration of CAPE was shown to attenuate inflammatory symptoms by inhibiting MSU crystal-induced caspase-1 activation and IL-1β production in air pouch exudate and foot tissue." (PMID 33603747, 2020). "Innate immune pathways are essential in the pathogenesis of gout, particularly the activation of NLRP3 inflammasome, which leads to the release of IL-1β and other pro-inflammatory cytokines." (PMID 33568990, 2020). "Studies suggest that the triggering of interleukin (IL)-1β release, which is activated by MSU stimulation and can further orchestrate a series of inflammatory cascade reactions, lies at the core of gout." (PMID 31590257, 2019). "miR-488 and miR-920 have also been demonstrated to be reduced significantly in gouty arthritis patients, possibly via the targeting of 3′-UTR of IL-1β." (PMID 30854012, 2019). "Further, the chicory extract significantly decreased IL-1β release by suppressing the NF-κB and NLRP3 signaling pathways in gout rats." (PMID 31590257, 2019). "Nonetheless, we found higher plasma levels of IL-1β, IL-1ra, IL-4, IL-6, IL-8, IL-9, IL-13, IL-17, FGF-basic, IFNγ, and TNFα in acute gouty arthritis patients." (PMID 31739430, 2019). "The inhibition of NLRP3 by QZTB, evidenced by the decreased mRNA and protein expressions of NLRP3 in the ankle joint, and the lower production of serum IL-1β and TNF-α level, further indicates the efficacy of QZTB on gouty arthritis in clinic." (PMID 31885675, 2019). "In humans, the production of IL-1β by resident macrophages is stimulated by MSU crystal and plays as a crucial role in the pathogenesis of gout." (PMID 30941135, 2019). "The gene expression of IL-1β and TNF-α, typical pro-inflammatory cytokines present in gout, was enhanced in BMDMs after exposure to MSU crystals at 4 h and 8 h, and their expression was higher in BMDMs from miR-146a KO mice than WT mice." (PMID 29544526, 2018). "An increased risk of incident MI in people with gout raises a question regarding the role of chronic inflammation and IL-1β pathways (via NLRP3 inflammasome activation) and CRP, hallmarks of gout, in the pathogenesis of MI." (PMID 29859125, 2018). "IL-1β is a major effector cytokine and plays a crucial role in the MSU-induced initiation of acute gout flares." (PMID 29482609, 2018). "Our present results also showed the significant production of pro-inflammatory cytokines, including IL-1β and TNF-α, in monocytes from patients with gout." (PMID 29056937, 2017). "In mouse gouty arthritis models, oral administration of CAPE suppressed MSU crystals-induced caspase-1 activation and IL-1β production in the air pouch exudates and the foot tissues, correlating with attenuation of inflammatory symptoms." (PMID 27934918, 2016). "Our present study demonstrated that MSU induced a transient increase in the secretion of IL-1β, which indicates a potential role for FLS in the inflammatory pathophysiology of gout." (PMID 25897296, 2015). "IL-1β was produced in monocytes by MSU crystals in vitro, and it was recently identified as a key cytokine in gout." (PMID 24999366, 2014). "In summary, the concentrations of ox-LDL and pro-inflammatory cytokines IL-1β, IL-6 and TNF-α significantly increased in gout patients in our study, while TGF-β concentrations significantly decreased in gout patients relative to controls." (PMID 24068523, 2014). "The study is to explore therapeutic effects of MSD on IL-1β and TNFα in THP-1 cells with MSU crystals-induced inflammation and to provide evidence for its use in gouty arthritis." (PMID 24999366, 2014). "Data from our study showed that rat with gouty arthritis induced by MSU crystal demonstrated an elevation in ankle swelling, synovial TNF-α, IL-1β mRNA, and protein levels." (PMID 23304232, 2012).
gout (continued). "A positive correlation was found between synergy in IL-1β production from PBMCs of patients between C18:0 and MSU crystals, as well as the annual number of attacks of acute gouty arthritis (rs: +0.649, P: 0.022)." (PMID 22762240, 2012). "When PBMCs of gout patients were incubated with MSU crystals together with Pam3Cys, production of IL-1β was significantly increased compared to Pam3Cys alone." (PMID 22762240, 2012). "Indomethacin, a drug often used as first-line therapies for acute inflammation in gouty arthritis, also reduced the TNF-α and IL-1β mRNA and protein levels in rats induced by MSU crystal." (PMID 23304232, 2012). "For IL-1β inhibitors that have been approved for clinical use like Canakinumab and Rilonacept, they are originally used to treat auto-inflammatory diseases like Familial Cold Auto-inflammatory Syndrome (CAPS) and gout." (PMID 41145465, 2025). "The combined trends of IL-1β and IL-6 suggest that IL-6 gene knockout attenuates the JAK2-STAT1/3 signaling pathway, inhibiting pro-inflammatory cytokine production and alleviating MSU-induced gouty arthritis." (PMID 40170729, 2025). "Similarly, acute gouty arthritis results from macrophage and neutrophil activation in response to monosodium urate (MSU) crystals, driving IL-1β–mediated sterile inflammation." (PMID 41404505, 2025). "IL-1β blockade, which reduced incident gout and atherosclerotic events, did not attenuate these associations." (PMID 39862678, 2025). "Although the inhibitory effect of SSG on Il-1β, Ifn-γ, and Cxcl10 was weaker than that of canakinumab, SSG more effectively promoted the release of anti-inflammatory factors compared to classic treatments of gout." (PMID 40417211, 2025). "Additionally, IL‐1β and TNF‐α immunofluorescence dual staining in gout and gout post‐OA synovial organoids was performed and imaged by laser confocal imaging." (PMID 39764563, 2025). "The best this topic has been studied is in the context of gout, an autoinflammatory condition characterized by monosodium urate (MSU) crystal-induced inflammasome activation and IL-1β release in macrophages, followed by neutrophil recruitment and NET extrusion." (PMID 40791588, 2025). "For example, targeting the JAK2/STAT3 signaling pathway could reduce the expression of pro-inflammatory cytokines like IL-6, IL-1β, and TNF-α, thereby alleviating gout symptoms and slowing disease progression." (PMID 39611154, 2024). "In addition, to verify the role of IL-37 in gout, THP-1 macrophages stimulated with recombinant IL-37 dose-dependently suppressed the activation of caspase-1 and IL-1β in MSU-induced inflammation." (PMID 39065733, 2024). "In gouty inflammation, the release of IL-1β produced via the activation of the inflammasome plays a key role; thus, we decided to approach an animal model of gouty arthritis induced by MSU crystals to mimic the characteristics of human gouty arthritis." (PMID 38474000, 2024). "Moreover, asymptomatic hyperuricemia population present the same level of IL‐1β and TNF‐α compared with patients with gout flare, highlighting the importance of physicians paying special attention to asymptomatic hyperuricemia." (PMID 36988248, 2023). "Furthermore, the ABCG2 gene played a crucial role in the aberrant generation of pro-inflammatory cytokines such as interleukin-1 beta (IL-1β), tumor necrosis factor-alpha (TNF-α) and IL-8 in gout." (PMID 36967798, 2023). "As predicted, gout synovial fluid served as an excellent positive control, because the inflammatory response to monosodium urate crystals leads to a NLRP3 inflammasome formation, caspase-1 activation and IL-1β release." (PMID 36936231, 2023). "Nowadays, the treatment of gout attack depends on drugs such as nonsteroidal anti-inflammatory drugs (NSAIDs), glucocorticoids, colchicine, and IL-1β antagonists." (PMID 37197585, 2023).
gout (continued). "In patients with gout, chronic deposition and presence of MSU crystals in the joints, facilitates on-going gouty flares underpinned by high systemic levels of NLRP3-derived IL-1β." (PMID 37106238, 2023). "Also, airpouch exudates have much reduced IL-1β and ASC, which are typical pro-inflammatory indicators that can also be detected in synovial fluids of gout patients." (PMID 36225929, 2022). "The initiation of gout occurs because of the interaction between MSU and resident macrophages, which activate the NLRP3 inflammasome complex, a regulator of the pro-inflammatory cytokine, IL-1β." (PMID 35400961, 2022). "Gout, a developed form of hyperuricemia, is usually characterized by persistent low-grade inflammation, since the crystalline urate can activate the NLRP3 inflammasome and contribute to IL-1β activation." (PMID 36245501, 2022). "Previous animal model studies using anakinra (IL-1R antagonist) suggested the possibility of targeting IL-1β to modulate MSU-induced inflammation, and early clinical studies also demonstrated efficacy in the treatment of acute and chronic gout patients." (PMID 35370689, 2022). "Dapansutrile may reduce the inflammatory response and the chemotaxis of inflammatory cells by blocking the activation of IL1B, CXCL8, and TNF for the treatment of gouty arthritis." (PMID 36105284, 2022). "Some of them are under investigation for inflammatory diseases such as Inzomelid for CAPS (phase I) (ClinicalTrials.gov Identifier: NCT04015076), OLT1177 for treatment of gout flares (phase II), and ZYIL1 for viral inflammatory diseases characterised by cytokine IL-1β flare." (PMID 36569900, 2022). "Z1456467176 achieved significant therapeutic effects in gout rats in vivo, although it did not completely inhibit BzATP-induced IL-1β secretion in vitro." (PMID 36052144, 2022). "Since IL-1β secretion is mainly mediated by activated NLRP3 inflammasome, we then examined inflammasome-dependent IL-1β secretion in culture supernatants of PBMCs from gout patients." (PMID 36052144, 2022). "In our study, injection of MSU crystals and feeding with HFD caused a decrease in the relative abundance of Bacteroides, which was significantly negatively correlated with the levels of UA, IL-1β, IL-6, TNF-α, MPO activity, and purine and pyrimidine metabolisms in mice with gout." (PMID 35145506, 2022). "In the pathological process of gout, the increased expression of XOD can promote the production of uric acid, disrupt the balance of oxidative stress, generate a large amount of ROS, activate the NLRP3 inflammasome, and release IL-1β." (PMID 36569836, 2022). "Although pathologically it has been firmly established that the activation of the NLRP3 inflammasome and IL-1β is important in the pathogenesis of gout, the interactive mechanism between MSU and cells has not been clearly elucidated." (PMID 35370689, 2022). "Although it is widely accepted that gout is an inflammatory disease characterized by urate crystal-induced NLRP3 inflammasome activation with up-regulated caspase-1 protease and IL-1β in macrophages, recent evidence has highlighted that serum IL-17 levels are significantly elevated in gout patients." (PMID 35197978, 2022). "Previous studies shown that IL-1β and TNF-αhave an important role in bone erosion of gout." (PMID 36567343, 2022). "Considering the important effect of pro-inflammatory cytokines on the development of acute gouty arthritis, we explored whether GPS could inhibit the release of IL-1β, IL-6, IL-18, and TNF-α." (PMID 34586567, 2022). "Similar to IL-1β monoclonal antibodies, canakinumab has been approved for several auto-inflammatory disorders, including classic SJIA (systemic juvenile idiopathic arthritis), gout, and macrophage activation syndrome." (PMID 36238162, 2022). "Ultimately, high concentrations of uric acid activate the innate immune response by overexpressing IL-1β in neutrophils and monocytes, which favors an acute episode of gout if urate homeostasis is not regulated." (PMID 35505381, 2022).
gout (continued). "In this study, similar results were revealed showing the decreased relative abundance of Lachnospiraceae and the significantly negative correlation between the relative abundance of Lachnospiraceae and the levels of UA, IL-1β, IL-6, TNF-α, MPO activity, and purine metabolism in mice with gout." (PMID 35145506, 2022). "Previous reports have shown that AM had anti-inflammation, anti-oxidation, anti-tumor, and anti-virus functions, and inhibiting IL-1β and ICAM-1 by AM may lead to gout suppression in MSU-induced HUVECs." (PMID 34079466, 2021). "Although the role of IL-1β in gout has already been established, mechanistic links between monosodium urate crystals and IL-1β production in gout have not been identified." (PMID 33493135, 2021). "In MSU-induced gouty arthritis in mice, orally administered CAPE significantly attenuated foot swelling and neutrophil infiltration in foot tissues, accompanied by decreased release of IL-1β and IL-18 and reduced levels of cleaved caspase-1 in foot tissues." (PMID 33535473, 2021). "Our results showed that the expression of IL-1β, TNF-α, and IL-6 was increased in the gouty rats, and the inhibitory effect of BV was similar to or better than that of Col, a treatment drug for acute gouty arthritis." (PMID 34564665, 2021). "In addition, JGT efficiently downregulated MSU crystal-induced swelling and pain and contrasted inflammation by suppressing pro-inflammatory cytokines (IL-1β, TNF-α, and IL-6) and MPO activity in a gouty arthritis mouse model." (PMID 33371241, 2020). "Compared with WT mice, St2-/- mice showed significantly reduced expression of IL-1β, IL-6, IL-13, CCL11, G-CSF, CXCL1, CCL2 and CCL3 proteins in ankle tissues, suggesting St2-/- mice showed generally attenuated inflammatory response during gout." (PMID 33204337, 2020). "Considering the connection between IL-1β and Caspase-1, flow cytometry was used to investigate whether BRD4 inhibitor have an impact on Caspase-1-dependent pyroptosis in animal model of gouty arthritis." (PMID 33162822, 2020). "Lack of autophagy and increase in proinflammatory IL-1β worsen the outcomes of subsequent exposure to an inflammatory stimuli in gout patients." (PMID 33322651, 2020). "Our results showed that gallic acid could reduce leukocyte infiltration, the expression of IL-1β and caspase 1 (p20) in joint tissues, as well as relieve inflammation in MSU-triggered gouty arthritis." (PMID 33365024, 2020). "IL-1β can activate other proinflammatory cytokines, including tumor necrosis factor-α (TNF-α) which is critical for the initiation and propagation of the inflammatory response in gouty arthritis." (PMID 31885675, 2019). "The pathogenesis of gouty arthritis has also been correlated with IL-1β via TNF-α, and NLRP3 inflammasome activation in macrophages and chemokines and an IL-1β antibody has been shown to provide superior inflammation prophylaxis than colchicine in patients with gout." (PMID 30854012, 2019). "Taken together, these data demonstrate that caspase-11 promotes the production and maturation of IL-1β during MSU injection in our gout model in a localized fashion and does not affect the phagocytosis of MSU." (PMID 31803174, 2019). "Besides, SMP-3 extract was able to prevent the paw edema, reduce gouty joint inflammatory features, and decrease the levels IL-1β, PGE-2, IL-8, and NO in gouty arthritis rats." (PMID 31379966, 2019). "During an acute episode of gouty arthritis, deposition of MSU crystals in joints stimulates resident macrophages to produce the inflammatory cytokine interleukin-1 beta (IL-1β) and inflammatory chemokines, interleukin-8 (IL-8), and monocyte chemoattractant protein-1 (MCP-1)." (PMID 31877739, 2019). "Therefore, we searched for orally available small-molecule drugs for gout treatment that inhibit the NLRP3 inflammasome, thereby blocking the production of active IL-1β." (PMID 31174271, 2019).